INS (insulin)
Diseases named in the same sentence as INS in open-access papers (continued):
Sharing a sentence is not in itself a finding about the gene and the disease.
Hyperinsulinemia (continued). "Furthermore, failure of hyperinsulinemia to normally suppress FFA is associated with impaired carbohydrate oxidation and muscle glucose storage, reduced hepatic insulin clearance and elevated triglycerides." (PMID 23434905, 2013). "The insulin hypothesis of hypertension proposes that the compensatory hyperinsulinemia that occurs with insulin resistance increases sodium reabsorption and sympathetic activity, which combine to cause elevated arterial pressure." (PMID 23573411, 2013). "The slopes of glucose concentration - response for C/I curves were similar between the N and DM, but significantly lower in the DYS group (right), indicating a higher level of saturation of the hepatic insulin extraction capacity probably due to the hyperinsulinemia." (PMID 23886319, 2013). "First, hyperinsulinemia and a high insulin-like growth factor-1 (IGF-1) level, which are caused by increased insulin, promote cell proliferation and inhibit apoptosis, contributing to the suppression of the hepatic synthesis of the sex hormone-binding globulin." (PMID 23826253, 2013). "This might be due to combined effect of defective uptake of glucose and hyperinsulinemia due to reduced hepatic degradation of normal quantity of secreted insulin." (PMID 22642663, 2012). "It is also known that significantly high insulin levels (hyperinsulinemia) with normal FBG are features of IR which may further be implicated in the development of CVD." (PMID 22899917, 2012). "Moreover, insulin is known to reduce protein degradation and amino acid levels Therefore, future in vivo studies are warranted that examine the effect of hyperinsulinemia while maintaining both euglycemia and euaminoacidemia." (PMID 22396763, 2012). "Hyperinsulinemia was defined by serum insulin levels ≥13.0 μU/mL and IR by HOMA-IR ≥2.60." (PMID 22770114, 2012). "Our study demonstrates that the rapid onset of hepatosteatosis, adipose tissue hypertrophy and hyperinsulinemia by ingestion of a diet high in fat and sucrose may possibly be due to the rapid response of lipogenic, insulin signalling and inflammatory genes." (PMID 22762794, 2012). "Mvt1 cells, both in vivo and in vitro, respond to hyperinsulinemia with increased expression of the transcription factor c-Myc, suggesting that high levels of insulin could increase the activity of this oncogenic factor in breast cancer." (PMID 22226054, 2012). "Chronic hyperinsulinemia has been shown to reduce acute insulin induced Akt-p in hepatocytes." (PMID 22590537, 2012). "However, hyperinsulinemia in FAAH−/− mice was evident indicated by their AUC for plasma insulin which was 3 times higher compared to wild-type mice." (PMID 22442717, 2012). "Furthermore, differences were observed in genes contributing to fatty acid, cholesterol and triglyceride metabolism and in genes involved in regulating lipolysis, between the insulin-resistant and -sensitive subjects especially during hyperinsulinemia." (PMID 22471940, 2012). "The resulting hyperleucinemia and hyperinsulinemia may exert leucine- and insulin-mediated stimulatory effects of prostate mTORC1 signaling." (PMID 22891897, 2012). "Additionally, FGF21 improved the diabetic phenotypes of these animals by decreasing hyperglycemia, hyperinsulinemia, glucose intolerance, and increasing peripheral and hepatic insulin sensitivity." (PMID 22792234, 2012). "Therefore the present study was undertaken to compare transcriptional differences in subcutaneous adipose tissue derived from obese insulin-resistant and lean insulin-sensitive women before and during euglycemic hyperinsulinemia." (PMID 22471940, 2012). "Such impairment of insulin signaling in prolonged hyperinsulinemia may result in ED and promote atherogenesis." (PMID 23497719, 2012). "The condition of hyperinsulinism and hyperandrogenism present in PCOS-IR patients could modulate the expression and/or the phosphorylation of proteins associated with the insulin pathway at endometrial level." (PMID 22390153, 2012).
Hyperinsulinemia (continued). "With the chronicity of the hyperinsulinemia, there is a downregulation in transportation mechanisms, which may explain why Alzheimer's patients have lower concentrations of insulin in the cerebrospinal fluid." (PMID 22389813, 2011). "As levels of expression of insulin in brain are modest compared to circulating levels, it is still believed that transport of peripheral insulin across the BBB and the consequences of peripheral hyperinsulinemia or hypoinsulinemia have significant roles in cerebral insulin signaling." (PMID 22654727, 2011). "Both IGF-1 and IGF-1R tend to have stronger mitogenic and antiapoptotic effects, and the hyperinsulinemia that occurs in insulin-resistant individuals may enhance this effect." (PMID 21773024, 2011). "Although a subset of Ran transgenic mice were asymptomatic (∼40%) at the time of diabetic onset (2 mo), these animals also revealed reduced islet number and islet mass, compensatory hyperinsulinemia, and impaired insulin response to glucose stimulation of isolated islets, in vitro." (PMID 22114719, 2011). "Induction of fetal hyperinsulinemia by direct infusion of insulin into the fetus by either fetal or maternal infusions of glucose resulted in significant increases in the activity of FTase and the amounts of farnesylated Ras in fetal liver, skeletal muscle, fat, and white blood cells." (PMID 21668983, 2011). "For example, until a more comprehensive analysis is conducted, we cannot formally exclude the possibility that deletion of IDE could trigger defects in insulin signaling components that in turn elicit compensatory hyperinsulinemia." (PMID 21695259, 2011). "Furthermore, hyperinsulinemia induced by transgenic overexpression of human insulin has been reported to result in impaired glucose tolerance." (PMID 21695259, 2011). "Indeed, brain concentrations of glucose and insulin are similar in both db/db and db/+ mice and remained unchanged after normalization of peripheral hyperinsulinemia." (PMID 21949705, 2011). "The suppressed thermogenesis is thus associated with establishment of a thrifty metabolism which spares glucose for catch-up fat via coordinated induction of insulin resistance in skeletal muscle, insulin hyperresponsiveness in adipose tissue and a state of hyperinsulinemia." (PMID 21244699, 2011). "Another mechanism is that obese women may be in a state of hyperinsulinemia, insulin being a growth factor for BC cells." (PMID 20842123, 2010). "Indeed, it has been shown that during GDM, the mother's glucose, after its passage via the foeto-placental barrier, induces the release of insulin from foetal pancreas and, thereby, produces foetal hyperinsulinemia." (PMID 20144210, 2010). "Additionally, the ingestion of the tea significantly reduced serum insulin level in diabetic patients with hyperinsulinemia whose serum insulin level was >17 μU/ml before intake." (PMID 20181067, 2010). "Insulin controled glycemia better than pioglitazone, but the latter, unlike insulin, provided renoprotection, perhaps due to the up-regulation of transforming growth factor beta (TGFβ) by hyperinsulinemia." (PMID 27713282, 2010). "Renoprotection was not necessarily associated with blood pressure or glycemic control but was associated with reduced AGE formation in most studies, with the exception of insulin, which induces hyperinsulinemia that eventually leads to overproduction of transforming growth factor beta." (PMID 27713282, 2010). "Hyperinsulinemia is believed to decrease renal sodium excretion to generate salt-sensitive hypertension; insulin stimulated the sodium-potassium adenosine triphosphatase pump and the sodium-hydrogen antiporter, two major renal tubular transports for sodium absorption." (PMID 19811354, 2009).
Hyperinsulinemia (continued). "Furthermore, our study shows that there is an altered relationship between ALK7 and INHBB expression in subjects with hyperinsulinemia, opening the possibility that activin B signaling is involved in metabolic control or that insulin affects the expression." (PMID 19275893, 2009). "Hyperinsulinemia is an early change in peripheral resistance to insulin." (PMID 19893948, 2009). "The inability of acutely administered Boc5 to elicit insulin responses under hyperinsulinemia may result from its poor potency as the compound is approximately 2700 times less potent than exenatide." (PMID 18682834, 2008). "Similarly, in the postprandial state, male rats showed hyperinsulinemia in the face of normal circulating glucose levels but demonstrated appropriate reduction of circulating insulin concentrations after fasting." (PMID 16203236, 2005). "Although fructose does not appear to acutely increase insulin levels, chronic exposure seems to indirectly cause hyperinsulinemia and obesity through other mechanisms." (PMID 15723702, 2005). "This marked hyperinsulinemia could be due to a combination of increased β-cell mass and decreased insulin clearance, as well as failure of insulin to suppress hepatic gluconeogenesis." (PMID 15287987, 2004). "The gender differences observed in this study, where males exhibited a higher prevalence of hyperinsulinemia and IR, as well as higher fasting insulin levels and HOMA-IR index compared to females, may result from a complex interplay of biological and societal factors." (PMID 40364246, 2025). "Similar basal overnight insulin delivery may have masked potential benefits by the time of testing, highlighting the need for further studies to refine strategies aimed at mitigating hyperinsulinemia’s adverse effects." (PMID 40045281, 2025). "Insulin dysregulation is a hallmark of equine metabolic syndrome (EMS), and in recent years, pharmacological treatment with sodium-dependent glucose transporter 2 inhibitors (SGLT2i) have shown promise in reducing the risk of hyperinsulinemia-associated laminitis in horses diagnosed with EMS." (PMID 41408266, 2025). "Therefore, metformin might mitigate hyperinsulinemia to some degree through direct β-cell AMPK activation in addition to the indirect outcome that is secondary to its insulin-sensitizing role." (PMID 40013621, 2025). "Chronic hyperinsulinemia, which may result from exaggerated insulin responses to rapidly absorbed starch in high-SAA individuals or from inefficient digestion and prolonged glucose absorption in low-SAA individuals, can downregulate insulin receptor sensitivity and disrupt metabolic homeostasis." (PMID 40806495, 2025). "Additionally, compensatory hyperinsulinemia may activate the insulin/IGF axis, stimulating cancer-promoting signaling pathways such as PI3K/Akt/mTOR." (PMID 40597094, 2025). "Additionally, a negative association between fasting insulin clearance and liver fat was observed, suggesting hepatic steatosis may impair insulin catabolism, exacerbating systemic hyperinsulinemia." (PMID 40502600, 2025). "Furthermore, hyperinsulinemia promotes cancer progression by activating the insulin/IGF-1 axis." (PMID 41310487, 2025). "Our study highlights the intricate interplay between insulin and IGF1 signaling in the hypothalamus and suggests that targeting IGF1 resistance may offer new therapeutic avenues for treating metabolic disorders associated with hyperinsulinemia." (PMID 40105689, 2025). "It was found that the hyperinsulinemic-euglycemic clamp test would cause excessive insulin levels in the circulation and exaggerate the PK data of injected insulin; the existing hyperinsulinemia might partially mask and delay the actual peak time of the tested insulin preparation." (PMID 40284414, 2025). "Additionally, these agents improve insulin sensitivity by reducing hyperinsulinemia, which may attenuate insulin-driven lipogenesis and hepatic fat deposition." (PMID 40289906, 2025).
Hyperinsulinemia (continued). "Additionally, chronic insulin therapy may contribute to β‐cell exhaustion through a paradoxical feedback mechanism—persistent peripheral hyperinsulinemia can downregulate endogenous insulin production while accelerating β‐apoptosis." (PMID 40919135, 2025). "However, insulin hypersecretion or hyperinsulinemia can also precede the development of IR, and the secondary IR may act as the downstream defense mechanism to reduce the metabolic stress to critical organs and prevent hypoglycemia." (PMID 40364246, 2025). "In PCOS patients with hyperinsulinemia (PCOS-HI) presenting with traditional Chinese medicine (TCM) syndromes of stomach heat and spleen deficiency, BXD exhibits comparable efficacy to metformin in reducing fasting insulin (FINS) levels and enhancing insulin sensitivity." (PMID 40102869, 2025). "Indeed, some studies indicate that hyperinsulinemia might increase the risk of AD by hindering the clearance of Aβ, as IDE becomes overwhelmed by excessive insulin." (PMID 40724942, 2025). "Molecular alterations associated with the diabetic phenotype, such as abnormalities in insulin signaling, which results in insensitivity to insulin and subsequent hyperinsulinemia, may ultimately favor tumor development through the regulation of HIF-1α, increased glucose uptake, and its utilization." (PMID 39996906, 2025). "Carbohydrate excess promotes hyperinsulinemia and adipose lipogenesis; fat overconsumption saturates adipose buffering, leading to ectopic lipid deposition; and protein, while generally supportive, can contribute to dysfunction when BCAAs accumulate in insulin-resistant states." (PMID 41470890, 2025). "Through this approach, we demonstrate the capability to not only sensitively detect deficiencies in insulin-stimulated exogenous glucose disposal but also identify subtle impairments in insulin-induced EGP suppression even without the presence of hyperinsulinemia." (PMID 39872987, 2025). "Although our study showed that insulin increases the cell-surface levels of URAT1 through AKT-mediated phosphorylation, stimulating urate transport, the data also highlight the multifactorial nature of the association between hyperinsulinemia and hyperuricemia." (PMID 40100301, 2025). "Notably, the extract exerted a marked effect on insulin levels: while the diabetic control group showed hyperinsulinemia, insulin concentrations in the extract-treated groups were significantly reduced, with the 300 mg/kg group achieving a 38% decrease, indicative of improved insulin sensitivity." (PMID 40895680, 2025). "Thus, changes in the quality of food and the excessive consumption of food and drinks, containing large amounts of sugars/sweeteners/iron, may lead to hyperinsulinemia and excessive pancreatic insulin secretion." (PMID 38791525, 2024). "However, hyperinsulinemia resulting from excess dietary nutrient consumption can stimulate increased adipose mass, and the resulting insulin can antagonize leptin signal transduction at the POMC neuron, driving increased energy intake and decreased energy expenditure." (PMID 38212644, 2024). "Moreover, hyperinsulinemia may impact extracellular Aβ levels by affecting insulin-degrading enzyme (IDE), preferentially degrading insulin over Aβ." (PMID 39683582, 2024). "However, in individuals with hyperinsulinemia, the excessive activation of insulin signaling pathways, including the phosphatidylinositol 3-kinase/protein kinase B (PI3K/AKT), mTOR, and Ras/mitogen-activated protein kinase (MAPK) pathways, significantly enhances tumor growth." (PMID 39290325, 2024). "Furthermore, IR fully liganded with insulin (i.e., four insulins per IR dimer) could efficiently clear insulin from the blood through receptor-mediated endocytosis, which may prevent hyperinsulinemia and hypoglycemia." (PMID 38521788, 2024).
Hyperinsulinemia (continued). "Since T1DM is different from the in obese and T2DM, especially considering the hyperinsulinemia, thus the antiatrophy ability of A. muciniphila may be dependent on the recovery of insulin signaling in muscle, evidenced by increased expression levels of Igf2r and Igf2bp1." (PMID 39429872, 2024). "In addition, hyperinsulinemia may lead to increased IGF-1 bioavailability due to insulin-mediated changes in IGF binding protein." (PMID 39012663, 2024). "However, it should be noted that one limitation of the HI-EG clamp is the potential reduction of insulin transport across the BBB, which may occur due to chronic hyperinsulinemia or other factors associated with peripheral IR." (PMID 38425702, 2024). "Additionally, the high FFA environment may induce insulin resistance, further augmenting blood pressure and insulin levels (hypertension and hyperinsulinemia), and elevating blood glucose, thereby increasing HbA1c levels." (PMID 39866803, 2024). "Consequently, reduced peripheral insulin-stimulated glucose disposal leads to compensated hyperinsulinemia which may further exacerbate IR." (PMID 39682351, 2024). "Furthermore, increased insulin (219.8 pmol/L, ref: 17.8–173 pmol/L) suggested hyperinsulinemia." (PMID 39095761, 2024). "Hence, the inexercise feeding strategy employed in DEC, which negated the need to inject exogenous meal-time insulin and circumnavigated the glycemic implications of the overt hyperinsulinemia that often accompanies post-prandially performed exercise in those with T1D." (PMID 39683492, 2024). "Furthermore, the mendelian randomization analysis suggested a causal relationship of DNA methylation in HK1 with HbA1c levels, supporting previous findings of HK1’s GWAS associations with HbA1c and HK1 pathways involving glucose, insulin signaling and hyperinsulinemia." (PMID 37679740, 2023). "However, it remains unclear whether APOε4 allele modification is due to hyperinsulinemia, and hence deeper insight is needed to understand the pathogenesis of AD and how the APOE genotype can influence insulin metabolism." (PMID 37372995, 2023). "At the age of 10–15 years, hyperinsulinemia appeared milder in the group with LEP deficiency as compared with the patients with LEPR and MC4R deficiencies (mean 49 versus 104 and 66 μIU/mL in children with LEP, LEPR, or MC4R deficiency, respectively) (range of insulin assay: 0–300 μIU/mL)." (PMID 37659411, 2023). "In addition, hyperinsulinemia may dysregulate central insulin signaling by reducing the insulin transport across the blood-brain barrier." (PMID 37932783, 2023). "Finally, in these PCOS women, serum HMBG1 levels slightly but significantly increased after short term exposure to marked hyperinsulinemia, induced by the glucose clamp procedure, with similar behaviors in insulin sensitive and insulin resistant subgroups of patients." (PMID 37256493, 2023). "In addition, reduced levels of melatonin could help to maintain hyperinsulinemia during the night in chronic infections, since insulin secretion is inhibited by its binding to the melatonin receptor on pancreatic β-cells." (PMID 37718435, 2023). "The loss of β-cells in DM implies that insulin secretion could be restored and hyperglycemia (but not hyperinsulinemia) normalized through the replacement or regeneration of the islets of Langerhans." (PMID 37873836, 2023). "This leads to an inevitable therapeutic increase in the dose of insulin therapy, resulting in exogenous systemic hyperinsulinemia, which stimulates androgen over-synthesis and secretion in the ovaries and adrenal glands, which in turn may lead to the development of PCOS." (PMID 37957681, 2023). "However, despite hyperinsulinemia, the action of insulin at the cellular level is impaired." (PMID 38203600, 2023). "Thus, fasting plasma insulin levels rise, and hyperinsulinemia eventually develops." (PMID 37960324, 2023).